CDH2 (cadherin 2)
Diseases named in the same sentence as CDH2 in open-access papers (continued):
Sharing a sentence is not in itself a finding about the gene and the disease.
tumor (continued). "After searching the database to review the literature about the tumor process according to the results of GO functional and pathway annotation of DE-S-Exo-miRNA target genes, 3 apoptosis genes (NTS, CDH2 and GRIA2) were identified." (PMID 30278585, 2018). "In comparison with the control group, except for miR-204-5p, the expression levels of ITGA2, FN1, ICAM1, CDH2, TIMP1, CLDN1, TNFRSF12A, miR-146b, and miR-222 were all up-regulated in the tumor group, consistent with the results of the bioinformatics analyses." (PMID 30414611, 2018). "At the molecular level, the epithelial biomarker CDH1 is downregulated, and the mesenchymal biomarkers N-cadherin (CDH2) and fibronectin (FN1) are upregulated in tumor buds, thus suggesting that tumor buds have mesenchymal characteristics." (PMID 28687755, 2017). "MED30 induced the expressions of EMT-related genes (N-cadherin; CDH2, P-cadherin; CDH3, twist related protein 1 and 2; TWIST1/2, vimentin; VIM), but inhibited the expression of E-cadherin (CDH1) a known tumor suppressor." (PMID 26110885, 2015). "Thus, over-expression of miR-218 could inhibit CDH2 expression and tumor cell mobility." (PMID 24705471, 2014). "The alterations of EMT-associated markers, such as: loss of epithelial genes CDH1, CDH3 and gain of mesenchymal genes CDH2 and FN1, as well as the adoption of a migratory mesenchymal phenotype were maintained in all the tumor-derived cell lines." (PMID 25361000, 2014). "N-cadherin (CDH2), the neuronal cadherin, stimulates cell-cell contacts during migration and invasion of cells and is able to suppress tumour cell growth." (PMID 23066729, 2012). "Moreover, analysis of gene expression across pathological stages showed consistent upregulation of CDH1, CDH2, and CDH3 in advanced tumor stages, emphasizing the potential role of cadherin genes in NSCLC progression." (PMID 40860670, 2025). "First, CDH2, the only gene with a positive coefficient value in the NSS, was noticed, and it was selected for validation of protein expression between tumor and adjacent non-tumor tissues." (PMID 40255563, 2025). "Concurrently, RT-qPCR analysis revealed that the expression levels of tumor proliferation markers (MCM2 and Ki-67) and epithelial-mesenchymal transition (EMT)-related markers (CDH2, VIM, and FN1) were also significantly elevated following TRPM6 knockdown, consistent with the phenotype assay results." (PMID 41562086, 2025). "Finally, the levels of genes involved in the tumor EMT, such as CDH2, CDH11, SMAD2, SMAD3, WNT9A, and SP-1, were significantly downregulated after the SH intervention." (PMID 41444284, 2025). "The N-cadherin gene (CDH2) is expressed in GBM and directly correlates with tumor grade." (PMID 40725030, 2025). "Factors shown to contribute to the development of LMD from CNS metastasis include genomic alterations independent of primary tumor site in MAPK, CDH2, and SF3BI displaying significant gain-, loss- and switch-of-function mutations, respectively." (PMID 38553702, 2024). "Therefore targeting CDH2 improved the efficacy of TIL-related treatment by decreasing PDL-1 and IDO-1, and indeed ADH-1 with TIL-treatment reduced tumour size and increased survival in the mouse models (Ref." (PMID 37132370, 2023). "Given that CHD1, CDH2, MMP2 and MMP9 play an important role in the process of EMT, we hypothesize that CCT8 mediate tumor metastasis through EMT." (PMID 37928427, 2023). "Similarly, high levels of CDH2 protein and ARF3 mRNA identified a patient group with lowest levels of new tumor formation after initial therapy, while all other groups showed similar rates." (PMID 36880595, 2023). "The ZEB1 knock-out in M13HS tumor cells was not correlated with the down-regulation of the EMT-related markers N-CADHERIN (CDH2) and VIMENTIN and up-regulation of miR-200c-3p." (PMID 38139138, 2023).
tumor (continued). "In addition, silent corticotroph PitNETs exhibit characteristics of epithelial to mesenchymal transition (i.e., N-cadherin (CDH2) and mesenchymal matrix markers (COL1A1, COL4A1)), pointing to an increased tumor migration potential." (PMID 36612109, 2022). "Moreover, CDH2 and FRMD3 expression were significantly higher in tumor tissues than in normal tissues, while hsa-miR-410-3p, hsa-miR-411-5p and hsa-miR-299-5p were significantly decreased in tumor tissues compared with normal tissues in THCA." (PMID 35756646, 2022). "GO and KEEG results showed that CDH2 and FRMD3 were strongly associated with immune-related functions, therefore, we considered that CDH2 and FRMD3 may play an important role in the tumor immune microenvironment." (PMID 35756646, 2022). "Next, we collected 28 paired clinically fresh THCA of carcinoma and paraneoplastic tissues, and the results showed that the mRNA expression of CDH2 and FRMD3 were significantly increased in tumor tissues compared with the paraneoplastic tissues by qRT-PCR assay." (PMID 35756646, 2022). "We also showed the correlation between CDH2 and FRMD3 expression and tumor immune infiltration." (PMID 35756646, 2022). "Then, the overexpression of circEPS15 suppressed tumor cell invasion and migration by inhibiting the TJP1/CDH2/VIM signaling pathway and retarded cell cycle progression, which was confirmed by the Transwell culture system, wound healing assays, flow cytometry and western blot assays." (PMID 35211158, 2022). "In an opposite manner, mRNA levels of some EMT markers such as Mmp2, Cdh2, and Acta2 are virtually absent in the ascites tumor cells." (PMID 34737944, 2021). "In addition, miR-765 mimics obviously down-regulated the expression of several EMT-related markers (e.g., COL3A1, FN1, CDH2, S100A4, MMP9, SNAIL and ZEB1) and up-regulated TJP1 expression in tumor lesions." (PMID 33859750, 2021). "Moreover, elevated levels of N-cadherin (CDH2), which increases the production of MMP9 to initiate the ideal environment for migratory tumour cells by rupturing the basement membrane in the tumour primary site, would eventually promote the migration process." (PMID 33073304, 2021). "This process of BHRF1+/SNHG8 high/miR-512-5p low/TRIM28high in EBVaGC directly enhances the activation of a set of tumor-promoting factors, such as proliferation-related genes (BCL-2, CCND1, PCNA, PARP1) and metastasis-related genes (Snail, VIM, CDH1, and CDH2)." (PMID 34722282, 2021). "Cadherin-2 (CDH2), a calcian-dependent cellular adhesion protein, preferentially mediates intercellular adhesion of homotypic cells, inhibits cell migration, and thus effectively inhibits tumor invasion and metastasis." (PMID 33732214, 2021). "We then quantified the expression of DNER, RBPJ, SKP1, CTNNB1, and CDH2 in solid tumor and paratumor paraffin sections by immunohistochemistry and found strong cytoplasmic positivity of DNER in tumor tissue compared with paratumor tissue, with significant differences (P < 0.05)." (PMID 33329729, 2020). "In contrast, EVs released by hypoxic cancer cells contained detectable levels of CDH2, which are typically not overexpressed by tumours under standard culture conditions." (PMID 33050615, 2020). "KLF4 wasdown-regulated in both tumor samples and mammospheres.Meanwhile, expression of NANOG was not changed inmammospheres, but it was down-regulated in tumors.Among EMT-related genes, CDH2, SNAIL1, TWIST1/2 andZEB1 were also overexpressed in mammospheres." (PMID 31376329, 2020). "Smaller tumour size and negative association with TGFB1, CDH2 and LLGL2 strengthen the tumour suppressive role of KANK1." (PMID 31679074, 2020). "We studied a retrospective cohort of 160 consecutive surgically treated NSCLC patients with available frozen tumor samples for expression of EMT markers (CDH1, CTNNB1, CDH2, and VIMENTIN), inducers (TGFB1, c‐MET, and CAIX), and transcription factors (EMT‐TF:SNAI1, SNAI2, ZEB1, TWIST1, and TWIST2)." (PMID 29845746, 2018).
tumor (continued). "Unlike prior EMT-focused studies that conceptualize cisplatin resistance as a uniform mesenchymal state, our single-cell RNA sequencing analysis reveals that CDH2 expression is selectively enriched in specific resistant tumor subpopulations rather than uniformly across all malignant cells." (PMID 41596365, 2026). "Expression of DNMT3B, PIWIL1, NANOG, OCT4, and CDH2 was significantly elevated in tumor samples compared to normal controls (p = 8.33 × 10−45, 1.01 × 10−23, 7.76 × 10−6, 3.22 × 10−54, and 1.82 × 10−22, respectively), indicating strong tumor-specific upregulation of these genes." (PMID 41596471, 2026). "Mesenchymal markers such as CDH2 (log2fc = 0.57) and DDR2 (log2fc = 0.63) are elevated in poor-prognosis tumours, suggesting that upregulation of mesenchymal genes may contribute to more aggressive tumour phenotypes." (PMID 41007296, 2025). "According to our RNA-seq data, in addition to CDH1/CDH2 (E-cadherin/N-cadherin), ICAM1 was upregulated in both T1M1 PDAC tissues and MET-containing CM-treated PDAC cells, which indicated that METs may affect tumour cell adhesion through ICAM1." (PMID 39025845, 2024). "While, e.g., DCAF7 and CDH2 displayed continuous changes across lineage types occurring during cancer progression, others such as TCIM or BRIP1 were expressed transiently at higher levels in asymmetric or only in symmetric (i.e., only invasive tumor cell) lineages, respectively." (PMID 38553478, 2024). "We identified ZNF471 as a novel potential tumor suppressor gene in CC that inhibits cancer cell growth, proliferation, invasion, and metastasis by arresting cell cycle progression and induction of EMT by up-regulation of CDH1 and downregulation of CDH2, VIM, and TW1." (PMID 33566221, 2021). "CDH2 expression was downregulated by romidepsin in tumor implants but not in cells." (PMID 33035223, 2020). "While no change in CDH1 and CDH2 expression was detected in the primary tumor tissue compared to normal colon tissue, vimentin SNAIL and TWIS showed high expression in the tumor tissue." (PMID 40566531, 2025).
cancer (1,323 papers, 1995 to 2026). A tumor composed of atypical neoplastic, often pleomorphic cells that invade other tissues. "Across cancers, N-cadherin (CDH2) upregulation is consistently linked to aggressive disease biology and poor survival outcomes." (PMID 41462674, 2025). "Cancer-associated fibroblasts (CAFs), marked by Col1a1, Cdh2, Epha6, and Prkch, were classified into two subtypes (CAFs 1 and 2)." (PMID 40723284, 2025). "Cdh2, a member of the Cadherin family, regulates many biological processes and has been proven to be closely associated with various cancers." (PMID 39364045, 2024). "Enhanced CDH2 expression is well known to associate with cancer cell motility, invasiveness and metastasis in different cancers." (PMID 34422665, 2021). "CDH1 and CDH2 are expressed in most normal tissues and reduced or loss of expression in cancer cells is well documented." (PMID 26011628, 2015). "The Cdh2 gene encodes N-cadherin (neural cadherin; abbreviated N-Cad) protein, a crucial mesenchymal marker that is upregulated during the ‘cadherin switch’, which ultimately leads to increased invasiveness and migratory properties in cancer cells." (PMID 38556549, 2024). "In particular, the peptidomimetic-designated Compound 15, a piperidin-4-amine which acts as a CDH2 antagonist, has been shown to induce apoptosis of MM, glioblastoma and pancreatic cancer cells, as well as fibroblast and cancer-associated death in vitro (Refs 38, 96)." (PMID 37132370, 2023). "A significant association of SOX11 and N-CADHERIN (CDH2) expression is also observed in genomic analyses across six cancer types, suggesting that mesenchymal pathways may be activated by SOX11 in both normal and cancer cells." (PMID 32909943, 2020). "As most human cancer is epithelial in origin, our focus will be E-cadherin and its related catenins, with occasional discussion on roles of other classical cadherins, such as neural cadherin (N-cadherin, encoded by CDH2) and vascular cadherin (VE-cadherin, encoded by CDH5)." (PMID 37255594, 2023). "Moreover, TRIM28 has been demonstrated to regulate EMT gene expression (CDH1 encoding E-CADHERIN and CDH2 encoding N-CADHERIN) through modification of histones of target gene promoters, further implying its role in acquisition of highly aggressive mesenchymal phenotype of cancer cells." (PMID 28851455, 2017). "By binding to the promoter of the CDH1 (E‐cadherin) gene, SNAIL1, SNAIL2, and ZEB2 suppress CDH1 expression and increase CDH2 (N‐cadherin) levels, reducing cell adhesion and promoting mesenchymal traits such as increased motility and invasion in cancer cells." (PMID 41244070, 2025). "Conversely, upregulation of CDH2 (N-cadherin) is commonly linked to the epithelial-mesenchymal transition (EMT), a key process that enables cancer cells to acquire an invasive phenotype." (PMID 40226617, 2025). "Among these, CDH1, CDH2, and CDH3 have been implicated in multiple cancers, yet their specific roles in NSCLC remain inadequately defined." (PMID 40860670, 2025). "Emerging evidence shows CDH2 junctions interact with β-catenin, RhoA/Rac1, and antioxidant pathways, enabling cancer stem cells to buffer ROS." (PMID 41462674, 2025). "The CDH2-centered RAX hub provides an integrative framework unifying three previously disconnected axes of cancer biology: redox dynamics, adhesion signaling, and exosome-mediated communication." (PMID 41462674, 2025). "Equally, the cadherin switch—downregulation of CDH1 (E-cadherin) and upregulation of CDH2 (N-cadherin)—is a hallmark of EMT that enhances migratory and invasive behavior across cancer types, including NSCLC." (PMID 40787462, 2025). "3.CDH2 (a substrate of FAM20C) is one of the markers of EMT that is associated with invasion and metastasis of cancer cells." (PMID 39790934, 2025).
cancer (continued). "The integration of adhesion, redox, and exosome–miRNA signaling within the CDH2-centered RAX hub converges on three malignant hallmarks: maintenance of cancer stemness, metastatic competence, and immune evasion." (PMID 41462674, 2025). "EMT plays an important role in the invasion and metastasis of various cancers including ATC, which is associated with upregulation of CDH2/N-cadherin and downregulation of CDH1/E-cadherin." (PMID 38500204, 2024). "Cancer patients with high cdh2 expression usually have poorer prognosis, while those with low cdh2 expression have improved prognosis." (PMID 39364045, 2024). "For instance, classical epithelial and mesenchymal genes, including KRT19, LOX, COL5A2, and CDH2, exhibited concordant compartmental switch between EM states in both the stem cell differentiation and cancer EMT cell line models." (PMID 38902393, 2024). "When autophagy is inhibited, the levels of mesenchymal markers, such as vimentin and CDH2/N-cadherin decrease, further confirming the influence of autophagy on cancer metastasis." (PMID 37834333, 2023). "Downregulation of the CDH1 gene and upregulation of CDH3, CDH2, and VIM in EMT is a hallmark of cancer metastasis." (PMID 37151391, 2023). "Next-generation CDH2 antagonists such as small-molecule inhibitors with improved potency and formulation are emerging as a unique class of anti-cancer therapeutics." (PMID 37132370, 2023). "Among the downstream genes, FN1, cadherin 2 (CDH2), EGFR, integrin subunit alpha 6 (ITGA6), and integrin subunit beta 4 (ITGB4), which are widely studied and are associated with cancer metastasis, were selected for further investigation." (PMID 37096833, 2023). "It is increasingly known that aberrant expression of CDH2 is closely related to malignant tumor processes such as apoptosis and metastasis and is thus considered a mesenchymal marker of the EMT phenotype." (PMID 37958584, 2023). "CDH2, a member of the cadherin family, mediates cancer cell invasion and metastasis; moreover, CDH2 is more expressed in patients with high grade and crPC compared to patients with low grade tumors." (PMID 35456552, 2022). "In terms of EMT marker expression, CDH1 was expressed at higher levels in the N-thy ori-3-1 cell line whereas CDH2 was more highly expressed in the cancer cell lines." (PMID 35118633, 2022). "Leukemia proliferation and protection from dexamethasone-induced apoptosis is dependent on cancer-niche interactions mediated by CDH2." (PMID 35977468, 2022). "Upon autophagy inhibition, the levels of mesenchymal markers including VIM (vimentin) and CDH2/N-cadherin undergo downregulation and further confirm the role of autophagy in cancer metastasis." (PMID 35317831, 2022). "In fact, mesenchymal-type cancer cells have low expression of epithelial markers like CDH1 and high expression of mesenchymal markers such as CDH2 gene encoding N-cadherin, fibronectin, and vimentin, among others." (PMID 36497132, 2022). "To validate the function of CDH2, we performed RNAi knockdown experiments on both cancer cells and i-niche cells." (PMID 35977468, 2022). "One significant feature of these phenotype cancer cells was their high expression of mesenchymal markers, such as CDH2, S100A4, MMP2, WNT5A, and ZEB1." (PMID 36553542, 2022). "The role of CDH2 in cell migration and invasion has been reported for several cancer cells, including BCCs." (PMID 34078741, 2021). "The discussed role of Cx43 and CDH2 in CSCs, which are associated with a dormant phenotype, led us to investigate how CDH2 contributes to Cx43-mediated gap junction for the purpose of long-term cancer cell survival in the BM." (PMID 34078741, 2021). "During epithelial mesenchymal transition (EMT), cancer cells can morphed in CSC-like phenotype with increased CDH2." (PMID 34078741, 2021). "The overexpression also caused a decrease in expression of cancer-promoting factors EZH2, DNMT1, FOXM1, EGFR, PCNA, AURKA, YAP1, and CDH2." (PMID 34595169, 2021).